CSPG4 (chondroitin sulfate proteoglycan 4)
Description:
Proteoglycan playing a role in cell proliferation and migration which stimulates endothelial cells motility during microvascular morphogenesis. May also inhibit neurite outgrowth and growth cone collapse during axon regeneration. Cell surface receptor for collagen alpha 2(VI) which may confer cells ability to migrate on that substrate. Binds through its extracellular N-terminus growth factors, extracellular matrix proteases modulating their activity. May regulate MPP16-dependent degradation and invasion of type I collagen participating in melanoma cells invasion properties. May modulate the plasminogen system by enhancing plasminogen activation and inhibiting angiostatin. Also functions as a signal transducing protein by binding through its cytoplasmic C-terminus scaffolding and signaling proteins. May promote retraction fiber formation and cell polarization through Rho GTPase activation. May stimulate alpha-4, beta-1 integrin-mediated adhesion and spreading by recruiting and activating a signaling cascade through CDC42, ACK1 and BCAR1. May activate FAK and ERK1/ERK2 signaling cascades.
Synonyms: MCSP; MCSPG; MEL-CSPG; MSK16; NG2; HMW-MAA; CSPG4A
Tractability: Antibody: its Gene Ontology location is reachable by antibodies, with high confidence; UniProt places it where antibodies can reach, with medium confidence; UniProt predicts a signal peptide or a membrane-spanning region; the Human Protein Atlas places it where antibodies can reach. PROTAC: ubiquitination databases record sites on it; its protein half-life has been measured.
Gene: Protein-coding gene on chromosome 15 (75,674,322 to 75,712,848, reverse strand). Ensembl gene ENSG00000173546.
Subcellular location: Cell membrane; Apical cell membrane; Cell projection, lamellipodium membrane; Cell surface
Subcellular location (Human Protein Atlas): Plasma membrane
Pathways (Reactome):
Disease: Defective B3GALT6 causes EDSP2 and SEMDJL1; Defective B3GAT3 causes JDSSDHD; Defective B4GALT7 causes EDS, progeroid type; Defective CHST14 causes EDS, musculocontractural type; Defective CHST3 causes SEDCJD; Defective CHSY1 causes TPBS
Metabolism: CS-GAG biosynthesis; CS/DS degradation; DS-GAG biosynthesis; Glycosaminoglycan-protein linkage region biosynthesis
Developmental Biology: Differentiation of Keratinocytes in Interfollicular Epidermis in Mammalian Skin
Gene Ontology:
Molecular function: protein binding; protein kinase binding; coreceptor activity
Biological process: intracellular signal transduction; positive regulation of peptidyl-tyrosine phosphorylation; nervous system development; signal transduction
Cellular component: cell surface; extracellular exosome; extracellular matrix; focal adhesion; extracellular region; Golgi lumen; lysosomal lumen; plasma membrane; apical plasma membrane; lamellipodium membrane; ruffle
Genetic constraint (gnomAD): Loss-of-function variants: 73 observed, 128.05 expected, observed/expected ratio (o/e) 0.57, 90% interval 0.47 to 0.69. The upper end of that interval is the gene's LOEUF score, 0.69, which puts it in group 2 of 6, group 1 being the genes least tolerant of losing a copy. Missense variants: 2,553 observed, 2,918.9 expected, observed/expected ratio (o/e) 0.87, 90% interval 0.85 to 0.9. Synonymous variants: 1,221 observed, 1,290.9 expected, observed/expected ratio (o/e) 0.95, 90% interval 0.9 to 0.99.
Homologues: Orthologues: chimpanzee CSPG4 (98% identical), macaque CSPG4 (97% identical), pig CSPG4 (88% identical), mouse Cspg4 (83% identical), rat Cspg4 (83% identical), guinea pig CSPG4 (82% identical), rabbit CSPG4 (80% identical), dog CSPG4 (68% identical), tropical clawed frog cspg4 (37% identical), zebrafish cspg4 (35% identical), Drosophila melanogaster kon (24% identical), Caenorhabditis elegans C48E7.6 (19% identical).
Diseases named in the same sentence as CSPG4 in open-access papers:
CSPG4 is named in the same sentence as 121 diseases in open-access papers, as found by Europe PMC text mining. Sharing a sentence is not in itself a finding about the gene and the disease. The quoted sentences say what the papers report.
melanoma (194 papers, 2006 to 2026). A malignant, usually aggressive tumor composed of atypical, neoplastic melanocytes. "In a later prospective study with hCSPG4-encoded plasmid for II/III-staged CSPG4-positive oral canine malignant melanoma, 42 dogs were subjected to en bloc resection." (PMID 40284831, 2025). "The observation holds true for CAR T cells of two different targeting specificities, adenocarcinoma-associated CEA and melanoma-associated CSPG4, demonstrating the generality of this concept." (PMID 40558528, 2025). "Prior work in human melanoma cell lines detected increased expression of CSPG4, also known as melanoma-associated chondroitin sulfate proteoglycan (MCSP) or neuron-glial antigen 2 (NG2), when ARSB activity was reduced." (PMID 37813168, 2024). "In dogs, the high molecular weight melanoma-associated antigen chondroitin sulfate proteoglycan-4 (CSPG4) was found to be a biomarker for malignant melanoma." (PMID 38645640, 2024). "Numerous reports have implicated CSPG4 as a potential target for the treatment of malignant melanoma, breast cancer, and glioblastoma." (PMID 38309500, 2024). "Some studies have shown that CSPG4 expression in malignant melanoma is related to the morphological changes associated with the epithelial-to-mesenchymal transition (EMT)." (PMID 38338902, 2024). "Another example of a skin-disease-relevant SNP-CpG-gene SME mediation involves CSPG4, or melanoma-associated chondroitin sulfate proteoglycan." (PMID 39137780, 2024). "CSPG4, a high-molecular-weight melanoma-associated antigen, is negatively associated with multiple targeted drugs, such as cell-surface proteoglycans." (PMID 37854594, 2023). "CSPG4 (also commonly referred to as NG2) interacts with the extracellular matrix and inordinate expression of CSPG4 is associated with cancers such as glioblastoma, melanoma and carcinoma." (PMID 36972308, 2023). "Melanoma-derived exosomes isolated with anti-CSPG4 express various melanoma associated antigens: Melan-A/MART-1, gp100, VLA-4 and TYRP2, which are absent in non-melanoma exosomes." (PMID 37022605, 2023). "Here, we report the identification and preclinical characterization of two distinct αβTCRs specific for the melanoma-associated antigen CSPG4 restricted by the highly prevalent HLA-C*07:01 allele (~30%)." (PMID 37849763, 2023). "The decrease of ARSB activity resulted in the overexpression of melanoma progression factors, such as chondroitin sulfate proteoglycan 4 (CSPG4) and pro-matrix metalloproteinase 2 (pro-MMP2), causing increased invasiveness of melanoma cells." (PMID 37601653, 2023). "Chondroitin sulphate proteoglycan 4 (CSPG4) is a cancer-associated protein highly expressed in melanoma cells that plays a major role in tumour growth, migration and neo-angiogenesis." (PMID 37022605, 2023). "Chondroitin sulfate proteoglycan 4 (CSPG4), also known as high molecular weight-melanoma associated antigen, is expressed in melanoma but also other tumor entities and constitutes an attractive target for immunotherapeutic approaches." (PMID 37849763, 2023). "For its features, we have focused our attention on CSPG4, as a promising tumor-associated antigen to target for effective anti-cancer vaccination against both canine and human melanoma." (PMID 35224082, 2022). "Cspg4 has been associated with VM in angiotropic melanoma cells and overexpression of Anpep in ovarian cancer cell lines has been associated with an enlarged vascular lumen in ovarian cancer xenografts." (PMID 36230774, 2022). "The CSPG4 proteoglycan was first identified in 1981, through serological and immunochemical testing of a melanoma-associated monoclonal antibody, as a highly immunogenic antigen expressed on human melanoma cell surfaces." (PMID 36428658, 2022). "CSPG4 is a well-established tumor-associated antigen in human melanomas, with a widespread expression on cancer cells, but absent in normal adult tissues." (PMID 35224082, 2022).
melanoma (continued). "While all three stromal populations expressed fibroblast markers, indicating that they represent melanoma CAFs, S3 also expressed some pericyte-associated markers such as Cspg4 (Ng2), Mcam, and Rgs5." (PMID 32433953, 2020). "In CSPG4-low WM1361 human melanoma cells, anti-CSPG4-(PDD) caused a slight decrease in cell viability at the highest concentration only (10 nM)." (PMID 32331483, 2020). "In BRAF-mutated human M21 melanoma cells, radiation induced B7-H3 level but there was limited modulation of CSPG4." (PMID 32894202, 2020). "A large proportion (i.e., ~70%) of malignant melanomas express the cell surface glycoprotein melanoma-associated antigen chondroitin sulfate proteoglycan (CSPG4)." (PMID 32331483, 2020). "The melanoma- and glioma-associated antigen chondroitin sulfate proteoglycan 4 (CSPG4) is overexpressed in 90% of melanomas and gliomas as well as in breast cancer." (PMID 30625226, 2019). "In melanoma, CSPG4 acts as an oncogenic driver, supporting growth and survival of melanoma cells, which reduces the risk of antigen-loss." (PMID 31779130, 2019). "In particular, we discuss merits and challenges associated with CSPG4-CAR-T cells for the ATT of melanoma, leukemia, glioblastoma, and triple-negative breast cancer." (PMID 31779130, 2019). "The B cell-derived clone showed binding comparable to that of a monoclonal antibody specific for the melanoma-associated antigen CSPG4." (PMID 29628923, 2018). "Although less well examined than melanoma, CSPG4 expression has also been associated with gliomas that originate from astrocytes, such as glioblastoma multiforme (GBM)." (PMID 29375561, 2017). "CSPG4 was associated with melanoma aggressiveness decades ago, and therapeutic efforts directed at inhibition of CSPG4 have been undertaken." (PMID 27926479, 2017). "The presence of soluble CSPG4 within circulation has been proposed as a potential diagnostic biomarker to aid melanoma detection and classification at the vertical growth phase." (PMID 29375561, 2017). "CSPG4 is the only well characterized cell surface melanoma-associated antigen and it has been examined as a potential target employing different therapeutic approaches." (PMID 29375561, 2017). "Early reports associated overexpression of CSPG4 with malignant melanomas, and more recently its enhanced expression has been identified in other cancer types." (PMID 29375561, 2017). "This tandem single-chain variable fragment antibody is designed to target human CD28 and the melanoma/glioblastoma-associated cell surface chondroitin sulfate proteoglycan 4 (CSPG4)." (PMID 26469402, 2015). "Expression of the transmembrane proteoglycan CSPG4 has been associated with melanoma formation and takes place in a number of normal tissues throughout development." (PMID 25537509, 2015). "CSPG4 is expressed on cancer cells as well as angiogenic vasculature and is associated with an aggressive disease course in several malignancies including melanoma and glioblastoma." (PMID 26469402, 2015). "In the context of melanoma, a notable example of this strategy includes antibodies designed to recognise the tumour-associated antigen chondroitin sulphate proteoglycan 4 (CSPG4)." (PMID 24969320, 2014). "Early clinical trials reported the development of anti-CSPG4 antibodies associated with prolonged survival of melanoma patients who responded to antibody therapy." (PMID 24969320, 2014). "Galectin-3 binds to N-linked oligosaccharides within the D3 domain of the CSPG4 core protein and to oligosaccharides on β1 to form a complex that can be immunoprecipitated from human melanoma cell surfaces." (PMID 24069584, 2013). "Chondroitin sulfate proteoglycan 4 (CSPG4) is a unique glycoprotein-proteoglycan complex that has been implicated in numerous aspects of melanoma cell biology and carcinoma (including HNSCC) with usefulness as a CSC in glioblastoma." (PMID 23533441, 2013).
melanoma (continued). "We have found that the expression of several known glial specific cell surface markers, such as NG2 (chondroitin sulfate proteoglycan 4, melanoma-associated, CSPG4), was upregulated in NAE." (PMID 18947415, 2008). "CSPG4 is a cell surface proteoglycan implicated in the regulation of several key oncogenic functions and frequently overexpressed in aggressive cancers, including melanoma and sarcomas, where its expression correlates with aggressive disease." (PMID 41375047, 2025). "Since 29% of patients show elevated circulating CSPG4 levels, it has been suggested that serum CSPG4 could serve as a diagnostic biomarker in melanoma." (PMID 39409881, 2024). "These contrasting results might be due to employing melanoma cell lines with differential CSPG4 expression, variable susceptibility to BRAF inhibition, or the use of different antibody clones and isotypes." (PMID 39409881, 2024). "The prevalence of the melanoma-associated antigen chondroitin sulfate proteoglycan 4 (CSPG4) expression is ~70%, therefore effective immunotherapies directed at CSPG4 could benefit many patients." (PMID 37185332, 2023). "The expression in not only primary but also metastatic melanoma cells further underlines the great therapeutic potential of targeting CSPG4, especially for treatment of metastatic melanoma, which is generally associated with poor prognosis and a median survival of less than one year." (PMID 37901209, 2023). "We have also shown that while CSPG4 expression in melanoma might be linked to pro-survival, a drop in expression in HNSCCs linked to the change in a tumour from a pre-metastatic to a metastatic clinical stage was also observed." (PMID 36428658, 2022). "Interestingly, examination of the TGCA data set revealed that higher CSPG4 expression in patient tissues is linked to significantly increased overall patient survival in melanoma (by Kaplan–Meier, * p = 0.0082)." (PMID 36428658, 2022). "This could cause a shutdown of melanoma cell proliferation within 3-4 days, which may be more pronounced in cells with high CSPG4 expression and also in low CSPG4-expressing cells through apoptosis and reduction in colony formation after 7 days." (PMID 32331483, 2020). "The tumor-associated antigen chondroitin sulphate proteoglycan 4 (CSPG4), a neural crest glycoprotein over-expressed on 70% of melanomas, contributes to proliferative signaling pathways, but despite highly tumor-selective expression it has not yet been targeted using ADCs." (PMID 32331483, 2020). "Hence, primary melanoma lesions as well as secondary metastatic lesions are susceptible to CSPG4-CAR-T cell therapy." (PMID 31779130, 2019). "Recent studies have also provided evidences of the positive impact of anti-CSPG4 mAb in improving the efficacy of anti-cancer drugs in glioblastoma and melanoma pre-clinical models, indirectly associating the CSPG4 expression with multidrug resistance in these tumor histotypes." (PMID 28668095, 2017). "Overexpression of the chondroitin sulfate proteoglycan 4 (CSPG4) has been associated with the pathology of multiple types of such as melanoma, breast cancer, squamous cell carcinoma, mesothelioma, neuroblastoma, adult and pediatric sarcomas, and some hematological cancers." (PMID 29375561, 2017). "Of the genes correlated with shorter survival, some were already known to be over-expressed in different types of cancer, such as MCM3, BCHE, and some have previously been implicated in melanoma progression, like CSPG4 and Cx26 or, more generally, associated with tumor invasiveness, like ADAMTS5." (PMID 17129373, 2006). "Therefore, immunotherapies targeting a melanoma-associated antigen, such as CSPG4, may effectively direct immune cells against cancer and address a significant unmet need." (PMID 37185332, 2023).
melanoma (continued). "The prognostic value of high CSPG4 expression has already been reported in melanoma, glioblastoma, breast cancer, head and neck squamous cell carcinomas, and hepatocellular carcinoma; however, and by contrast with our result, CSPG4 expression was associated with poor prognosis." (PMID 35267618, 2022). "Thus, mAbs specific for CSPG4, otherwise known as “High Molecular Weight Melanoma-Associated Antigen, generated and tested by Dr. Soldano Ferrone (currently at Harvard University), represents a unique melanoma-specific, rigorously characterized reagent." (PMID 34207762, 2021). "CSPG4 overexpression is particularly associated with mid-to-late transformation stages, from proliferative to early invasive and migratory stages of tumor progression, such as in the progression of melanoma tumors from radial growth phase (RGP) to vertical growth phase (VGP)." (PMID 28657611, 2017). "As a consequence, the elimination of citrate-boosted melanoma cells by CSPG4-specific CAR-T cells was augmented in the presence of gluconate." (PMID 42198246, 2026). "Although this study does not directly investigate the degradative axis, previous work in melanoma models has shown that CSPG4 can facilitate cell invasion through activation of membrane-bound MMP complexes, potentially including MMP-14, at the cell surface." (PMID 40724839, 2025). "The cell surface antigen chondroitin sulfate proteoglycan 4 (CSPG4) is expressed on 90% of melanoma tumors and metastases, as well as on sarcomas, astrocytomas, gliomas, neuroblastomas, and leukemia." (PMID 39764559, 2025). "In vivo, the administration of CSPG4‐specific CAR‐T cells to mice bearing melanoma cells significantly stunted tumor growth and improved overall survival." (PMID 40700516, 2025). "The SPION‐loaded CAR‐T cells maintained their killing capacity against melanoma cells expressing the CAR‐specific antigen chondroitin sulfate proteoglycan (CSPG4)." (PMID 39764559, 2025). "DNA vaccines targeting chondroitin sulfate proteoglycan 4 (CSPG4) are another immunotherapeutic approach under investigation for canine melanoma." (PMID 41394861, 2025). "This spheroid inhibition was not limited to melanoma, as CSPG4-positive breast cancer spheroids also exhibited reduced spheroid growth in the presence of CAR-MαCSPG4 compared to control CAR-MGFP." (PMID 40082557, 2025). "These vaccines aim to stimulate immune responses against CSPG4-expressing melanoma cells and are being evaluated for both cutaneous and oral malignant melanomas." (PMID 41394861, 2025). "Regarding the healthy epidermis adjacent to nevi and melanomas, CSPG4 showed only slight cytoplasmic expression in common melanocytes of the skin." (PMID 40700516, 2025). "Over the last decades, several immunotherapeutic approaches targeting CSPG4 have been developed and tested in different tumor types, with melanoma being the most extensively studied." (PMID 41375047, 2025). "We provide evidence that CSPG4-targeting CAR-Ms inhibit melanoma growth in immune-compromised animals over 18 days from the last CAR-M injection, well after CAR-Ms are no longer detected in the tumor." (PMID 40082557, 2025). "To generate melanoma‐targeting CAR‐T cells, we electroporated mRNA encoding a CAR specific for CSPG4 into human CD3+ T cells." (PMID 39764559, 2025). "To assess the presence of surface proteins on melanoma-derived exosomes, we first employed CSPG4, a well-established surface marker for melanoma exosomes, using a bead-based flow cytometry assay." (PMID 40805206, 2025). "Taken together, these results suggest that combining CSPG4-targeting CAR-Ms with αCD47 approaches result in robust inhibition of melanoma growth in 3D by increased phagocytosis." (PMID 40082557, 2025). "Chondroitin sulfate proteoglycan 4 (CSPG4) is a promising target for melanoma immunotherapy, but its expression in benign melanocytic lesions and its diagnostic value remain unexplored." (PMID 40700516, 2025).